CRP (C-reactive protein)
Diseases named in the same sentence as CRP in open-access papers (continued):
Sharing a sentence is not in itself a finding about the gene and the disease.
Sepsis (continued). "Serum PCT and C-reactive protein (CRP) levels are widely used as specific biomarkers for diagnosis of bacterial infection-related inflammation, but they are limited in their ability to distinguish sepsis from other inflammatory conditions." (PMID 33628853, 2021). "This study evaluated MDW as a biomarker for sepsis and compared it with CRP and PCT." (PMID 33857210, 2021). "Moreover, the cutoff value of CRP ≥40 mg/dL is often used to predict sepsis in emergency departments, as well as treatment failure among patients with exacerbated mild to moderate chronic obstructive pulmonary disease." (PMID 33606735, 2021). "According to the findings of this study, PCT is more sensitive than CRP in detecting sepsis early." (PMID 34912626, 2021). "Additionally, CRP and IL-6 possess limited abilities to distinguish sepsis from other inflammatory conditions or to determine prognosis." (PMID 34055659, 2021). "During the time course of polytrauma management surgery and definitive care, the CRP level might variate, and at some point in time, the diagnosis of sepsis might be set." (PMID 34884171, 2021). "The inability to distinguish MIS-C from sepsis using IL-6, CRP, and PCT could delay immunomodulatory treatment for MIS-C or inappropriate immunosuppression in sepsis." (PMID 34869111, 2021). "Laboratory tests such as blood count, C-reactive protein (CRP), serum electrolytes and protein profile offer little help with the differential diagnosis in the presence of diseases with symptoms similar to non IgE-mediated FA (e.g., sepsis, gastroenteritis)." (PMID 33466746, 2021). "CRP is an acute phase reactant, and increased circulating CRP levels follow rising levels of cytokines (e.g., interleukin-6, tumor necrosis factor-a), which are sustained in the course of sepsis." (PMID 34439240, 2021). "Traditional individual markers of sepsis, like the entire leukocyte count, neutrophil count, and CRP, lack the specificity to permit them to discriminate between those patients with an inflammatory response to trauma or surgery, for instance, and people with a new infection." (PMID 34912626, 2021). "Procalcitonin (PCT) and C-reactive protein (CRP) are the main biomarkers for diagnosing sepsis." (PMID 34233608, 2021). "Thus, a number of studies have investigated the relationship between the serum CRP/albumin ratio and inflammatory diseases such as sepsis, cancer, acute pancreatitis, ulcerative colitis, hepatitis B, and CAD." (PMID 33453709, 2021). "CRP estimation has now an established value as a marker of neonatal septicemia." (PMID 34899922, 2021). "PON1 and CRP were, respectively, significantly lower and higher in dogs with sepsis compared with polytraumatized and clinically healthy dogs (p < 0.001 for both the analytes), and also in dogs with trauma compared with healthy dogs (p = 0.011 and p = 0.017, respectively)." (PMID 34072427, 2021). "Some biomarkers, such as C-reactive protein (CRP) and procalcitonin (PCT), have been widely used as an acute phase reactant in critically ill patients, but their diagnostic and prognostic values for sepsis are limited." (PMID 33803628, 2021). "Hence, this study evaluated the diagnostic value of MDW in predicting sepsis and compared it with those of other biomarkers, such as white blood cell (WBC) count, CRP, and PCT, and clinical scores (qSOFA) for detecting early sepsis." (PMID 33857210, 2021). "However, little is known about the performance of MDW and how it compares to those of the most frequently used sepsis biomarkers: C-reactive protein (CRP) and procalcitonin (PCT)." (PMID 34193208, 2021). "Furthermore, recent studies were inconclusive about the usage of CRP as a salivary biomarker for detection of sepsis in neonates." (PMID 33673378, 2021). "The mean s-CRP levels were 98 mg/L in sepsis patients and 70 mg/L in SIRS patients." (PMID 34675320, 2021).
Sepsis (continued). "Moreover, the cutoff value of CRP level >40 mg/dL was used to predict sepsis in emergency departments and demonstrated a sensitivity of 82.3% and specificity of 38.7%." (PMID 33606735, 2021). "To demonstrate the clinical relevance of LPS model with respect to sepsis, we measured total white blood cell count, and serum CRP and PCT levels, several typical blood biomarkers for diagnosis of sepsis, in piglets at different time points (1, 2, 4, 8, 12, and 24 h) after LPS challenge." (PMID 33431831, 2021). "Another pro-inflammatory protein present in sepsis EVs is C-reactive protein (CRP)." (PMID 34451925, 2021). "In orthopedics, acute infection, particularly sepsis, could be detected early and treated based on the CRP level checked during hospital admission." (PMID 34830626, 2021). "CRP is an acute-phase protein synthesized by the liver, induced by cytokines like IL-6, and its level in the blood increases within hours in response to inflammation and sepsis." (PMID 34205667, 2021). "Although suPAR has been found to be significantly elevated in critically ill patients, including patients with sepsis, compared to healthy controls, the ability of blood suPAR levels to discriminate sepsis from non-sepsis patients was poor compared to that of CRP." (PMID 34925360, 2021). "CRP is closely related to infection and related to many factors in the diagnosis of sepsis." (PMID 34233608, 2021). "Its levels may further increase in burn patients with infection or sepsis, thus previous studies have suggested CRP as a good predictor of sepsis in burn patients." (PMID 33654698, 2021). "Acute intoxication features may overlap with sepsis or encephalitis, which may warrant sepsis work up such as full blood count, C-reactive protein (CRP) and cultures based on the focus of infection." (PMID 34405068, 2021). "The most important role of CRP use is in the follow-up of sepsis children." (PMID 33108806, 2021). "However, recent evidence has shown that CRP has drawbacks in the specific diagnosis of sepsis in severely burned patients." (PMID 33654698, 2021). "Furthermore, we investigated if CPD at t0 were correlated with C-reactive protein (CRP), patient survival, or complicated sepsis course." (PMID 33777867, 2021). "The level of CRP was reported to have little correlation with the severity of illness in sepsis." (PMID 34720754, 2021). "Furthermore, a previous report comparing predictive accuracy of NLR and CRP for suspected late-onset sepsis in preterm neonates showed that NLR is superior to CRP in detecting culture-proven cases of sepsis." (PMID 33603568, 2021). "On adjusted level, non-Omani nationality, ARDS, sepsis, high CRP and need for NIV and steroids use were associated with severe disease." (PMID 35076497, 2021). "The resulting CRP AUROC values were 0.69 for REBA Sepsis-ID and 0.64 for BC." (PMID 32850901, 2020). "However, a study conducted by Jedynak and co-workers suggested that sTREM-1 was outperformed by both CRP and IL-6 for the diagnosis of severe sepsis and septic shock, although sTREM-1 did outperform PCT for the diagnosis of severe sepsis." (PMID 32164268, 2020). "Interleukin-6 (IL-6) and C-reactive protein (CRP) are being used for diagnosis of sepsis." (PMID 33233806, 2020). "The CRP 2 at cut-off 8.01 mg/L showed the highest diagnostic performance for identification of culture negative clinical sepsis cases with sensitivity (90.4%), specificity and PPV (100%), and NPV (97.3%)." (PMID 33233806, 2020). "Although many biomarkers in sepsis including lactate, proinflammatory cytokines, chemokines, C-reactive protein, and procalcitonin have been identified, the diagnosis still lacks specificity because of the complicated, dynamic changes during severe sepsis and septic shock." (PMID 33344646, 2020).
Sepsis (continued). "For discriminating sepsis vs. medical events with low inflammation and trauma patients at the identified best cut-off, CRP had highest sensitivity, specificity, NPV, and PPV, although TNFR2 demonstrated equally high sensitivity in discriminating sepsis from trauma patients." (PMID 32948801, 2020). "Two studies investigated the use of IL-6 along with PCT and CRP for the diagnosis of sepsis." (PMID 32164268, 2020). "CWA could therefore complement or replace existing pro-inflammatory markers such as C-reactive protein and procalcitonin in the diagnosis of bacterial infection and sepsis." (PMID 32843693, 2020). "The remarkable diagnostic performance of both nCD64 and presepsin in our study, comparable to the conventional sepsis parameters including hs-CRP, and CBC indices, suggests their potential utility as reliable markers for early diagnosis of NS; this was supported by other study results." (PMID 33204274, 2020). "Of the 228 neonates with suspected sepsis, 94 (41.2%) had a positive CRP." (PMID 32238170, 2020). "Next, we tested if a combination of MRproADM with established and routinely used markers such as CRP, PCT, and IL6 could increase the diagnostic accuracy for sepsis using a composite score." (PMID 32831638, 2020). "IPF has been reported to have a comparable efficiency to C-reactive protein (CRP) in discriminating patients who had sepsis and those who had not and to be predicting the risk of developing sepsis in patients admitted to intensive care unit." (PMID 32821576, 2020). "The authors noted that suPAR had higher specificity than either PCT or CRP, meaning that it may be useful in ruling out sepsis in suspected cases; its use in combination with other biomarkers could therefore provide a more powerful diagnostic approach." (PMID 32164268, 2020). "Increase of CRP level (C-reactive protein) over 50 mg/dl could be observed in nine patients (50%), three of them developed a sepsis." (PMID 32447349, 2020). "Laboratory sepsis evaluation included highly sensitive CRP (hs-CRP), CBC, in addition to nCD64 (flow cytometry technique), and presepsin measurement (CLEIA technique combined with Magtration® technology); the diagnosis was confirmed thereafter by positive blood culture results (BacT/Alert system)." (PMID 33204274, 2020). "Traditionally, CRP is the most frequently used biomarker to diagnose sepsis or infection." (PMID 32220241, 2020). "Significant increase in nCD64 and hs-CRP results were present in sepsis groups compared to the disease controls (P < 0.001); nCD64 at 43% cutoff value could detect the presence of sepsis with 85.6% sensitivity and 93% specificity." (PMID 32832553, 2020). "A myriad of molecules has been under investigation in the early discrimination of sepsis, including C-reactive protein, procalcitonin, cytokines and surface markers of circulating leukocytes, which could be promising biomarkers in the diagnosis of sepsis." (PMID 31931717, 2020). "According to this study findings, PCT, CRP, and IL-6 were shown to be highly significantly elevated in the confirmed sepsis cases when compared with the suspected cases, which proved not to be infected by both blood culture and PCR (p ≤ 0.001, p=0.001, p=0.004 respectively)." (PMID 33061986, 2020). "Previous studies have already found that CRP levels are significantly higher in sepsis patients across the different clinical severity groups, thus further investigations with different subgroup analysis or cutoff levels in different severity groups are warranted." (PMID 33198109, 2020). "CRP is stable in serum or plasma and is typically used to diagnose infection and sepsis." (PMID 32103450, 2020). "So, the high CRP level maintains longer in sepsis patients in this study." (PMID 32508526, 2020).
Sepsis (continued). "The authors measured the levels of PSEP, CRP, and PCT in blood samples obtained from 19 sepsis cases and 74 non-sepsis control cases, and the comparison of the values observed showed that, compared to CRP and PCT, PSEP is even a superior biomarker for the post-mortem diagnosis of sepsis (p < 0.01)." (PMID 33092081, 2020). "Finally, we did not have enough information to compare the performance of the L/A ratio with validated ICU scoring systems such as APACHE II as well as other prognostic markers often used in sepsis such as procalcitonin and CRP." (PMID 33072780, 2020). "Although CRP is a marker of the acute inflammatory response, rather than of the infection that caused the sepsis, it is used to assess the severity and progression of sepsis-induced inflammation." (PMID 32778146, 2020). "It was also reported that neither the PCT test nor the CRP test was used to diagnose the cause of febrile neutropenia, except in cases of severe sepsis." (PMID 32908505, 2020). "Further studies will need to assess whether markers of innate immune activation, like sTREM-1, have superior sepsis-related outcome prediction compared to more general inflammation markers such as procalcitonin and C-reactive protein." (PMID 32605575, 2020). "In order to analyse the diagnostic potential of MRproADM for identification of sepsis, we performed ROC analyses comparing MRproADM with clinically established and routinely used markers such as procalcitonin (PCT) and C-reactive protein (CRP)." (PMID 32831638, 2020). "In addition to its reported utility in both early-onset and late-onset sepsis, besides, the high sensitivities and specificities were documented when combined with the hematological indices and CRP." (PMID 33204274, 2020). "Besides, the combination of NLR and CRP improved the diagnosis of early sepsis in study participants." (PMID 33178505, 2020). "Interestingly, the likelihood of sepsis was increased 18 times by the combination of CRP ≥4.0, lymphocyte count <0.45 and platelet count <150." (PMID 32867031, 2020). "In addition, an increase in IL-6 levels and a decrease in CRP levels were detected with increasing PMI (post-mortem interval) in sepsis cases." (PMID 33092081, 2020). "Furthermore, severity scores of SAPS 3 and SOFA, as well as the C-reactive protein level were higher in the sepsis group." (PMID 32492832, 2020). "The CRP 2 at cut-off 8.01 mg/L showed the highest diagnostic performance for identification of culture negative clinical sepsis cases." (PMID 33233806, 2020). "Therefore, the caseload included also a low number of dogs on which the diagnosis of sepsis was presumed on the basis of the final diagnosis and/or on the presence of changes in inflammatory markers of inflammation such as CRP and/or PON-1." (PMID 33363227, 2020). "In addition, PBMC miR-10a was at least as good as PCT and CRP in differentiating sepsis and infection." (PMID 32214905, 2020). "In spite of the little diagnostic value of sepsis on the first day, we find the continuation of the high CRP level correlated with the existence of sepsis: the CRP levels in Group A (AC with sepsis) are higher than those of other groups from day 2 to day 10 (P < 0.05)." (PMID 32508526, 2020). "Procalcitonin (CALCA) C-reactive protein, interleukin (IL)-6, and soluble urokinase-type plasminogen activator receptor may serve as sepsis markers." (PMID 32636717, 2020). "After sepsis, systemic levels of C-reactive protein (CRP) and soluble programmed death ligand 1 (a marker of immunosuppression) are elevated for up to one year in patients while interleukin 6 (IL6) and IL10 persists for several months in human and experimental models." (PMID 33969227, 2020). "In addition to PCT and CRP, more than 100 different molecules have emerged as potentially useful biomarkers for sepsis." (PMID 32850901, 2020). "Therefore, we have carried out our study to search for better markers than CRP for the diagnosis of sepsis." (PMID 33061986, 2020).
Sepsis (continued). "Although the presence of chills, the C-reactive protein (CRP) level, and the quick Sequential (Sepsis-Related) Organ Failure Assessment (qSOFA) score have been identified as potential predictors of bloodstream infection, none has been determined to have adequate specificity and sensitivity." (PMID 32000694, 2020). "The rise in serum CRP and the drop in Hb levels may signify increased haemolysis, sequestration in the lung or possibly sepsis." (PMID 32051480, 2020). "Could insulin be a biomarker of sepsis in newborn like C reactive protein and procalcitonin which are known biomarkers of sepsis." (PMID 32637004, 2020). "We assume that CRP synthesis in the liver might persist because of the longer treatment time of sepsis than local infection." (PMID 32508526, 2020). "Since frailty status influences CRP levels in older persons with sepsis, we could also speculate that CRP levels are casual common pathways of frailty and delirium in older persons hospitalized for infectious diseases." (PMID 32244301, 2020). "Daily measurements of CRP levels may also facilitate the monitoring of the course of severe sepsis in patients." (PMID 32220241, 2020). "A recent single-center clinical trial involving patients with sepsis suggested that CRP may be a useful marker to guide antibiotic treatment time, when compared to a PCT strategy." (PMID 32487263, 2020). "However, compared to CRP and PCT, the diagnostic accuracy of the NLCR to detect sepsis in ICU patients in this study is low and therefore the NLCR seems less suitable in predicting presence of sepsis in this vulnerable patient category." (PMID 30811475, 2019). "Therefore, in order to increase the accuracy of sepsis diagnosis, physicians should survey for other indicators such as biomarkers (e.g., CRP, PCT), imaging data (e.g., X-ray), and organ dysfunction." (PMID 31036824, 2019). "We inferred that the relationship between AGP and CRP resides in the fact that they are secreted by the same cytokines, such as IL-1, IL-6, and glucocorticoids, to promote anti-inflammatory effects during early sepsis." (PMID 31309103, 2019). "CRP is an acute phase protein that is elevated in trauma patients, and numerous studies have suggested that CRP can be utilized to predict the development of sepsis." (PMID 30918528, 2019). "Sepsis is a condition of complex physiological changes, and to ensure areliable diagnosis, other laboratory criteria should be evaluated, such as bloodculture, inflammatory markers, such as C-reactive protein or prolactin, whenfeasible." (PMID 30916236, 2019). "Only CRP showed significant higher in septic shock group than sepsis group." (PMID 31309103, 2019). "We performed a systematic review and meta-analysis to evaluate the diagnostic accuracy of neutrophil CD64, comparing it with C-reactive protein (CRP) and procalcitonin (PCT) for the diagnosis of infection in adult patients with septic syndrome, based on sepsis-2 criteria." (PMID 30623257, 2019). "Current studies focus on the identification of early biomarkers to predict sepsis outcome, including serum C-reactive protein (CRP), procalcitonin (PCT) levels, and acute physiology and chronic health evaluation II scores (APACHE II) and sequential organ failure assessment scores (SOFA)." (PMID 31771650, 2019). "While there is a general consensus on the increase of PTX3 plasma levels in septic patients, and the correlation with severity from SIRS to sepsis and septic shock, the diagnostic superiority of PTX3 over other biomarkers, such as PCT, IL-6, CRP and lactate, is still under debate." (PMID 31031772, 2019). "While C-reactive protein (CRP) is a well-studied marker for predicting treatment response and mortality in sepsis, it was aimed to assess the efficacy of the neutrophil lymphocyte ratio (NLR) as a predictor of mortality and treatment response in sepsis patients in the intensive care unit (ICU)." (PMID 31648506, 2019).